TNF (tumor necrosis factor)
Diseases named in the same sentence as TNF in open-access papers (continued):
Sharing a sentence is not in itself a finding about the gene and the disease.
Insulin resistance (continued). "Considering that both TNF-α and resistin confer insulin resistance, CAPE seems to interfere with obesity-induced insulin resistance." (PMID 31805752, 2019). "WAT M1 macrophages generate pro-inflammatory cytokines, such as tumor necrosis factor α (TNFA-α) and interleukin 6 (IL6), thus contributing to the induction of insulin resistance." (PMID 31614949, 2019). "Pro-inflammatory cytokines such as, tumor necrosis factor-α (TNF-α), reduce the insulin-stimulated tyrosine phosphorylation of the insulin receptor and IRS-1, impairing insulin action and inducing insulin resistance." (PMID 30871083, 2019). "Our results indicate that high-glucose load leads to glucose intolerance with insulin resistance through impairment of GLP-1 secretion, increase of blood glucose levels via activating TLR4 and increasing levels of IL-6 and TNF-α in mice." (PMID 31138952, 2019). "Insulin resistance-induced hyperinsulinemia and IGF-1 can further enhance the biological effects of TNF-α by activating the TNF-α signaling pathway." (PMID 31440472, 2019). "COX-2/PGE2 pathway strongly triggers the production of pro-inflammatory cytokines such as TNF-α and MCP-1 corresponding to increasing insulin resistance." (PMID 30621146, 2019). "Elevated levels of pro-inflammatory biomarkers such as TNF-α, interleukin-6 (IL-6) and interleukin-8 (IL-8), and C-reactive protein (CRP) have all been reported in various insulin resistance states." (PMID 29955954, 2019). "When periods of overnutrition are sustained, abnormal production of adipocytokines (e.g., leptin, adiponectin, and TNF-α) or hepatokines with diabetogenic properties (e.g., fetuins, RBP4, and selenoprotein P) intensify peripheral insulin resistance." (PMID 31771244, 2019). "After 6 weeks, Alanine aminotransferase (ALT), glucose, insulin, HOMA IR (Homeostatic Model Assessment for Insulin Resistance), FFA (free fatty acids), Tumor necrosis factor alpha (TNF α), IL6, IL1B levels were measured in blood." (PMID 31496048, 2019). "After the 4 week intervention, besides increased concentration of cholesterol and ALT, we observed an increase in insulin resistance (HOMA-IR, 1.3 ± 0.4 vs. 0.95 ± 0.31, HFHCh group vs. control) and increased TNF-α concentration." (PMID 31783667, 2019). "To further assess the role of FGF-1 in TNF-α-induced hepatic insulin resistance in vivo, we injected FGF-1 into wild-type mice treated with TNF-α." (PMID 31866871, 2019). "Emerging data suggest that TNF-α, FFA and hyperinsulinemia, which induce insulin resistance, activate er307 phosphorylation on IRS-1 and inhibit its function." (PMID 30871060, 2019). "HFB-fed mice showed signs of impaired glucose metabolism and insulin resistance along with a significant elevation in the concentration of triglycerides, LDL-cholesterol, total cholesterol, IL1β, TNF-α, IL-6, and leptin in serum." (PMID 30319558, 2018). "When AGEs occur in serum albumin, they can bind to the AGE receptor (RAGE) on monocytes and trigger the release of tumor necrosis factor-α (TNF-α), leading to insulin resistance." (PMID 29996539, 2018). "It is also well documented that the release of inflammatory cytokines, such as tumor necrosis factor-α (TNF-α) and interleukin-6 (IL-6), which are often cited as crucial cytokines that mediate insulin resistance, can be induced by chronic stress." (PMID 29433422, 2018). "On the other side, decreased IL-10 has been related to elevated serum concentrations of TNF-α, increased proportion of Mon-CD11c+CD206− over the Mon-CD11c−CD206+ subpopulation, hyperglycemia, and higher levels of insulin resistance in obese subjects." (PMID 29675435, 2018). "There have been studies highlighting proinflammatory cytokines, such as tumor necrosis factor α (TNF-α) released by white adipose tissue (WAT), leading to insulin resistance (IR)." (PMID 30425749, 2018).
Insulin resistance (continued). "Myeloid-specific Iκκ-β (an activator of NF-κB)-deficient mice have shown decreased NF-κB activation and pro-inflammatory cytokine production (IL-1β, IL-6, TNF-α, and MCP-1), leading to inhibition of the development of insulin resistance." (PMID 30443223, 2018). "Serum levels of insulin, Apelin, glucose, tumor necrosis factor-α(TNF-α), interleukin-1β (IL-1β) and the homeostasis model assessment of insulin resistance (HOMA-IR) were alsomeasured using commercial kits." (PMID 29845798, 2018). "In addition, XBP1s abolished palmitate-induced insulin resistance in adipocytes by increasing adiponectin secretion, repressing the secretion of pro-inflammatory adipokines such as leptin, monocyte chemoattractant protein 1, and tumor necrosis factor α, and decreasing fatty acid release." (PMID 30111834, 2018). "In fact, hepatic insulin resistance was observed in mice showing overexpression of MCP-1 in the adipose tissue, along with increased release of inflammatory cytokines such as TNFα and IL-633." (PMID 30451856, 2018). "Among the cytokines released, tumor necrosis factor (TNF)-α and interleukin (IL)-6 stands out for their contribution to insulin resistance development." (PMID 30618824, 2018). "To study the influence of inflammation on hepatic insulin resistance, we determined the levels of MCP-1, C-reactive protein (CRP), IL-6 and TNF-α." (PMID 29028831, 2017). "Increased level of IL-6, TNF-α and CRP are thought to contribute to the development of insulin resistance, T2DM, and CVD." (PMID 28125601, 2017). "Both FA and SIB reduced the adipocyte size, as wellas the circulating levels of adipokines, TNF-α and MCH-1, which would explain itsameliorating effect on abdominal adiposity and insulin resistance." (PMID 28076453, 2017). "Celastrol showed improvement in insulin resistance and renal injury via inhibition of NF-κβ pathways and inhibiting expression of inflammatory mediators like IFNγ, NOX4, TLR4, and TNF-α." (PMID 29163178, 2017). "Insulin resistance is induced by phosphorylation of serine residues (Ser 307/612/632) of IRS-1 by diabetes-inducing factors such as fatty acids, and TNFα." (PMID 29165364, 2017). "The patients classified as being insulin-resistant had higher inflammatory markers (CRP, TNF-alpha, and IL-6) and higher disease activity: mean DAS28 score in the non-IR group was 3.6, and in the IR group it was 4.6." (PMID 28932748, 2017). "M1 ATMs produce pro-inflammatory cytokines, such as tumor necrosis factor α (TNFα), interleukin (IL)-6, and monocyte chemoattractant protein (MCP)-1, thus contributing to the induction of insulin resistance." (PMID 28440284, 2017). "Our present study showed that the administration of ECD and LGZGD has preventive effect against hepatic insulin resistance in vivo and in vitro by decreasing of IRS-1Ser307 and TNF-α." (PMID 28630632, 2017). "Overexpression of tumor necrosis factor-alfa (TNF-α) in adipose tissue is a common correlate of TNF-α and insulin resistance in animal models." (PMID 28587303, 2017). "Systemic inflammation, with elevated markers such as C-reactive protein (CRP), tumor necrosis factor-α (TNF-α) and interleukin-6 (IL-6), plays an important role in both, the progression of COPD and the development of insulin resistance." (PMID 27335596, 2016). "Ceramides like reconstituted low density lipoprotein ceramide 24:0 were found to increase TNF-α, IL-1β, IL-6, and MCP-1 in vitro and to induce insulin resistance in lean mice." (PMID 26788518, 2016). "CCL2 plays a crucial role in the recruitment of macrophages into WAT and upregulation of TNF-α, IL-6 and CCL2 in WAT is critically involved in the induction of systemic insulin resistance." (PMID 26871288, 2016).
Insulin resistance (continued). "Besides, we have also found that antitumor necrosis factor-α (anti-TNF-α) agents may improve insulin resistance in patients with moderate-to-severe psoriasis, although no significant changes in serum leptin or resistin concentrations after 6 months of adalimumab therapy were found." (PMID 27293954, 2016). "In particular, phosphorylation of p38 MAPK is stimulated by the pro-inflammatory cytokines, TNF-α, IL-1β, and MCP-1, while activation of the JNK signaling pathway correlated with insulin resistance and pancreatic β function." (PMID 27929393, 2016). "It is known that an increase of pro-inflammatory molecules (TNF-α, IL-6, MCP-1, and IL-1) directly secreted from adipocytes is related to insulin resistance and chronic inflammation." (PMID 26927041, 2016). "Plasma TNFα can cross the BBB and lead to cerebral insulin resistance by inhibiting IRS-1 phosphorylation at tyrosine residues." (PMID 27884163, 2016). "These macrophages, probably stimulated by cellular debris, assume an inflammatory phenotype, also known as classic or M1, characterized by the expression of proinflammatory cytokines (TNFα, IL1 and IL6), which aggravate insulin resistance." (PMID 27437032, 2016). "The proinflammatory cytokine tumor necrosis factor-α (TNF-α) is synthesized and released by adipocytes and has been shown to play a role in the induction of insulin resistance." (PMID 26942201, 2016). "Through enhancement of adiponectin and inhibition of TNFα release, PPAR-γ improves the insulin resistance state in obese subjects." (PMID 27983705, 2016). "TNF-α then activates c-Jun N-terminal kinase (JNK), which, in turn, inhibits Akt activity and leads to insulin resistance." (PMID 27608037, 2016). "Most studies found that subjects with insulin resistance, prediabetes, or T2DM had increased levels of IL-6, TNF-α, and hs-CRP." (PMID 27478850, 2016). "Exercise increases the secretion of interleukin-6 (IL-6) from muscle cells, which has anti-inflammatory effects through inhibition of TNF-α and IL-1β, and reduces TNF-induced insulin resistance." (PMID 27485519, 2016). "In adipocytes, TNFα treatment was reported to induce an increased abundance of GM3 in the cell membrane, and this increased abundance of GM3 was found to produce insulin resistance." (PMID 26338710, 2015). "Data demonstrated that salicylate significantly improved retinal function, as well as reduced TNFα and SOCS3-induced insulin resistance in all samples." (PMID 25874611, 2015). "Based on prior work demonstrating that TNFα activates SOCS3 and SOCS3 can induce insulin resistance through activation of insulin receptor via phosphorylation on tyrosine 960, we measured both SOCS3 and IRTyr960 in the lean and obese animals." (PMID 25874611, 2015). "ATMs, a major source of inflammatory mediators such as TNF-α and IL-6, play critical role in WAT inflammation and in the development of insulin resistance." (PMID 25816341, 2015). "However, whether PP4 is involved in TNF-α-induced hepatic insulin resistance remains unclear." (PMID 26666849, 2015). "First, BMI percentile was positively correlated with insulin resistance (fasting insulin and HOMA-IR), lipid profiles (LDL-c, TG and TC), and inflammatory markers (hs-CRP, MCP-1, TNF-α, PAI-1, and leptin) but negatively correlated with adiponectin level." (PMID 26011530, 2015). "There were positive correlations between NAFLD and insulin resistance index (HOMA-IR), free fatty acids (FFA), tumor necrosis factor-α (TNF-α), omentin-1, visceral fat area, homocysteine (HCY), and serum uric acid (UA)." (PMID 26566287, 2015). "Inflammatory cytokines (e.g., TNFα, MCP-1, IL-6) worsen insulin resistance and inflammatory signaling in mice." (PMID 25816097, 2015). "On the other hand, to examine the role of PP4 in hepatic insulin resistance in vivo, we established a mouse insulin resistance model by treating C57BL/6J mice with TNF-α." (PMID 26666849, 2015).
Insulin resistance (continued). "Those outcomes were homeostasis model assessment for insulin resistance (HOMA-IR) and Ferriman-Gallwey scale, fasting glucose, fasting insulin and glucose/insulin ratio, lipid profile and TNF-alpha, acne, infertility, and weight gain and testosterone level." (PMID 25653680, 2015). "In the correlation analysis, BMI percentile was positively correlated with insulin resistance (fasting insulin level and HOMA-IR) and inflammatory markers (hs-CRP, MCP-1, TNF-α, PAI-1, and leptin levels) but negatively correlated with the adiponectin level." (PMID 26011530, 2015). "Correspondingly, TNF-α concentration correlated with the degree of stunting in girls, and IL-6, CRP and insulin resistance correlated with the degree of stunting and adiposity in boys in South Africa." (PMID 26445018, 2015). "Pio reduced TNF-α and SOCS3-activated insulin resistance pathways in the retina and protected against diabetic retinopathy." (PMID 26336514, 2015). "In the present study, we did not report any significant difference in protein expression of TNF-alpha, IL-6 and SOCS3 during HFD-induced cardiac insulin resistance." (PMID 26539824, 2015). "No significant intervention effect was observed for adiponectin, insulin resistance, or inflammatory markers (CRP, IL-6 and TNF-a) although the findings were inconclusive." (PMID 25706622, 2015). "Hepatic knock-down of PP4 in vitro and in vivo as well as suppression of PP4 activity ameliorated TNF-α-induced insulin resistance, whereas over-expression of PP4 promoted insulin resistance." (PMID 26666849, 2015). "Adipocyte-induced increase of TNF-α and PAI-1 is responsible for a prothrombogenic status and insulin resistance in obese people." (PMID 25759691, 2015). "However, since the discovery of increased of tumor necrosis factor alpha (TNFα) in adipose tissue from obese individuals, this tissue has become the focus of numerous studies on the secretion of proinflammatory cytokines and consequent pathobiologies including insulin resistance." (PMID 26648664, 2015). "CLE significantly decreased fasting blood glucose, glucose level in OGTT and IPITT, plasma insulin, homeostatic model assessment-insulin resistant (HOMA-IR), TNF-α, IL-6, FFA, TG and TC levels, and hepatic glycogen content in db/db mice." (PMID 25889508, 2015). "Subsequent increases in the release of pro-inflammatory adipokines/chemokines such as TNFα and MCP-1 as well as free fatty acids from adipocytes promote inflammation of adipose tissue and lead to insulin resistance in peripheral tissues." (PMID 25706552, 2015). "Although mechanisms involved in TNFα-induced insulin resistance are not completely understood, compelling evidence indicates that TNFα inhibits IRS-1- and IRS-2-mediated PI3-kinase activation, leading to insulin resistance." (PMID 26077338, 2015). "Our finding in this study revealed that FDW consumption, in a month, induced insulin resistance index (IRI), hyperinsulinemia a serum proinflammatory cytokines values such as IL6 and TNF in male rats." (PMID 26170888, 2015). "In fact, some studies have reported abnormally high circulating levels of inflammatory cytokines including IL-6, IL-8, IFN-γ, and TNF-α in obese individuals exhibiting OSA and insulin resistance/type 2 diabetes." (PMID 25944984, 2015). "It rapidly became clear that early proinflammatory effects of HF diet, such as elevated TNF-α, could serve as a trigger for subsequent inflammation or insulin resistance through activating NF-kB and other inflammatory pathways involved in the etiology of insulin resistance and Type 2 diabetes." (PMID 25861245, 2015). "Increased VAT acts as a metabolically active tissue that produces numerous inflammatory cytokines such as hs-CRP, tumor necrosis factor alpha (TNF-α), and interleukin-6 (IL-6) and promotes both hepatic and systemic insulin resistance." (PMID 25111123, 2014).
Insulin resistance (continued). "Elevated circulating levels of tumor necrosis factor-α (TNF-α), interleukin-6 (IL-6), and high-sensitivity capsular reactive protein (hs-CRP), which can impair insulin resistance and thereby reduce glycemic control, have been shown in a previous study." (PMID 25147841, 2014). "This occurs because it abolishes the stimulatory effect of TNFα on JNK1/2 kinase, which is directly involved in the development of insulin resistance." (PMID 24565471, 2014). "This metabolic inflammation is characterized by a moderate excess in cytokine production, including interleukin (IL)-6, IL-1, or tumor necrosis factor alpha (TNF-α), that injures cellular insulin signals and contributes to insulin resistance and diabetes." (PMID 24808896, 2014). "Inflammatory molecules generated in adipose tissue, such as TNF-α and IL-6, are related to decreased GLUT4 expression, which leads to insulin resistance due to decreased adipocyte glucose uptake." (PMID 24398136, 2014). "While the resulting fat deposits can accelerate insulin resistance through autocrine release of TNFα, TWEAK can inhibit this process by blocking TNF-mediated activation of JNK." (PMID 24550918, 2014). "MetS group mice also presented with insulin resistance and systemic inflammation, as measured by increases in HOMA-IR and serum TNF-α level, respectively." (PMID 24490784, 2014). "Many pro-inflammatory cytokines, such as TNF-α, IL-6 and IL-1β, have been demonstrated to be elevated in T2DM patients and participate in the development of insulin resistance." (PMID 24759263, 2014). "Activin A has also been proposed to have a pro-inflammatory effect, stimulating the secretion of TNF alpha and IL6 cytokines, both well-known important players in the pathogenesis of insulin resistance." (PMID 24763182, 2014). "Exercise confers protection against TNF-α induced insulin resistance while it reduces CRP, IL-6, and TNF-α levels and increases anti-inflammatory substances such as IL-4 and IL-10." (PMID 24563869, 2014). "It is known that TNF-alpha, IL-6, and CRP play an important role in insulin resistance and the vascular inflammation process through their multiple actions." (PMID 24249586, 2014). "Several studies suggest that TNF-α and IL-6 improve lipolysis and the secretion of FFA, which promotes insulin resistance by interfering with glucose transport and insulin action." (PMID 25053966, 2014). "The two groups were well matched for BMI and circulating levels of biomarkers involved in glycaemic control, indices of insulin resistance, inflammation (IL-6, CRP, TNF-α, MIF), oxidative stress and SpO2." (PMID 24733551, 2014). "Regular physical activity suppresses tumor necrosis factor - alpha (TNF-α) production by fat tissue and thereby offers protection against TNF-α-induced insulin resistance." (PMID 25233867, 2014). "Many of them, including monocyte chemotactic protein (MCP)-1, tumor necrosis factor (TNF)-α, interlukin (IL)-1, IL-6 and IL-8, have been reported to promote insulin resistance." (PMID 24733068, 2014). "Tumor necrosis factor alpha (TNF-α), as well as interleukin-1 & 6 (IL-1 & IL-6) are known to play a major role in the pathophysiology of insulin resistance in T2DM." (PMID 25528960, 2014). "The adipocyte death rate was associated with parallel increases in weight, numbers of ATMs (expressing CD11c), TNFα and MCP-1 levels, and insulin resistance." (PMID 23577240, 2013). "In order to determine the effect of IGFBP-3 on TNF-α-induced insulin resistance, adipocytes were infected with IGFBP-3 alone and in the presence of TNF-α and insulin." (PMID 23383064, 2013). "An increase of IL-6 (p = 0.015) and TNF (from 49.7 to 53 pg/mL), and decrease of plasma APO (7658 to 5152 ng/mL) and exacerbation of insulin resistance (p = 0.007) were noted." (PMID 22829443, 2013).